TFPI (tissue factor pathway inhibitor)
Description:
Inhibits factor X (X(a)) directly and, in a Xa-dependent way, inhibits VIIa/tissue factor activity, presumably by forming a quaternary Xa/LACI/VIIa/TF complex. It possesses an antithrombotic action and also the ability to associate with lipoproteins in plasma.
Synonyms: EPI; LACI; TFPI1; TFI
Tractability: Antibody: a drug acting on it is in phase 2 or 3 trials; its Gene Ontology location is reachable by antibodies, with high confidence; UniProt places it where antibodies can reach, with medium confidence; UniProt predicts a signal peptide or a membrane-spanning region. PROTAC: ubiquitination databases record sites on it; its protein half-life has been measured; a small molecule that binds it is known. Other modalities: an approved drug acts on it.
Gene: Protein-coding gene on chromosome 2 (187,463,823 to 187,565,846, reverse strand). Ensembl gene ENSG00000003436.
Subcellular location: Secreted (Isoform Alpha); Microsome membrane (Isoform Beta)
Pathways (Reactome):
Hemostasis: Initiation of coagulation cascade; Regulation of clotting cascade
Gene Ontology:
Molecular function: endopeptidase inhibitor activity; serine-type endopeptidase inhibitor activity; peptidase inhibitor activity
Biological process: cellular response to steroid hormone stimulus; negative regulation of blood coagulation; blood coagulation; cellular response to lipid
Cellular component: caveola; cell surface; extracellular region; plasma membrane
Genetic constraint (gnomAD): Loss-of-function variants: 10 observed, 30.4 expected, observed/expected ratio (o/e) 0.33, 90% interval 0.2 to 0.56. The upper end of that interval is the gene's LOEUF score, 0.56, which puts it in group 2 of 6, group 1 being the genes least tolerant of losing a copy. Missense variants: 247 observed, 320.33 expected, observed/expected ratio (o/e) 0.77, 90% interval 0.69 to 0.86. Synonymous variants: 91 observed, 109.86 expected, observed/expected ratio (o/e) 0.83, 90% interval 0.7 to 0.99.
Homologues: Orthologues: chimpanzee TFPI (99% identical), macaque TFPI (94% identical), pig TFPI (77% identical), rabbit TFPI (71% identical), dog TFPI (67% identical), rat Tfpi (61% identical), mouse Tfpi (59% identical), zebrafish tfpia (33% identical), Caenorhabditis elegans C02F12.5 (15% identical), Caenorhabditis elegans K12G11.6 (15% identical), Caenorhabditis elegans Y55F3BR.2 (12% identical), Drosophila melanogaster CG7565 (11% identical), and 1 more. Paralogues in human: TFPI2 (26% identical), AMBP (22% identical), SPINT1 (22% identical), WFIKKN1 (21% identical), WFIKKN2 (21% identical), SPINT2 (15% identical), KIAA0319L (14% identical), WFDC8 (13% identical), EPPIN (12% identical), KIAA0319 (11% identical), LRP11 (11% identical), SPINT4 (9% identical), and 1 more.
Diseases named in the same sentence as TFPI in open-access papers:
TFPI is named in the same sentence as 157 diseases in open-access papers, as found by Europe PMC text mining. Sharing a sentence is not in itself a finding about the gene and the disease. The quoted sentences say what the papers report.
Sepsis (48 papers, 2006 to 2025). Sepsis is defined as life-threatening organ dysfunction caused by a dysregulated host response to infection. "Of note, in a recent analysis from septic shock patients, high TFPI levels were associated with overall sepsis disease severity and particularly with acute kidney injury (AKI), liver dysfunction as well as high levels of D-Dimer and lactate." (PMID 39478586, 2024). "While we didn’t find any variants of IL1RN or CD14 to be associated with sepsis, we found two variants of tissue factor pathway inhibitor (TFPI), an anticoagulant protein, to be associated with Sepsis-2, but not Sepsis-3." (PMID 35275946, 2022). "Sepsis is often associated with coagulation abnormalities, and the antithrombin system, the activated protein C system, and the tissue factor pathway inhibitor (TFPI) are heavily disorganized." (PMID 32801997, 2020). "It is no wonder why clinical trials using antithrombin agents, APC, recombinant TFPI and recombinant TM was unsuccssful in sepsis-associated coagulopathy." (PMID 31160889, 2019). "The aim of this study was to characterize the fluctuations in the levels of natural anticoagulants, particularly TFPI, in the course of sepsis and to find out their association with the anticoagulant action of the low-molecular-weight heparin enoxaparin." (PMID 26377606, 2016). "The aim of this study is to assess the diagnostic and prognostic values of TF and TFPI in patients with sepsis and sepsis-induced ARDS." (PMID 26025445, 2015). "We compared the allele and genotype distributions of all SNPs in TF and TFPI between the sepsis and severe sepsis patients." (PMID 25407675, 2014). "The objective of this study was thus to evaluate the association of TF and TFPI polymorphisms with the development and outcome of severe sepsis in the Chinese Han population." (PMID 25407675, 2014). "Additionally, in TFPI conditional knockout mice, TFPI deficiency worsened sepsis-induced ALI/ARDS and reduced survival rates." (PMID 38664775, 2024). "Injury to endothelial cells and the destruction of the glycocalyx due to the suboptimal synthesis of TFPI may induce the activation of coagulation, accelerating the development of sepsis-associated DIC." (PMID 36673595, 2023). "Similarly, elevated TFPI plasma levels are associated with overt DIC in patients with sepsis, in contrast to the reduced TFPI expression by endothelium." (PMID 37081895, 2023). "The measurement of functional TFPI levels, in addition to protein levels, may provide further insight into the role of TFPI in sepsis-associated DIC." (PMID 36673595, 2023). "Tissue factor (TF) and tissue factor pathway inhibitor (TFPI) play a central role in the endothelial permeability regulation and dysfunction, which is associated with the development of sepsis and acute lung injury/acute respiratory distress syndrome (ALI/ARDS)." (PMID 26025445, 2015). "Thus, the objective of this study was to assess the prognostic and diagnostic value of plasma TF and TFPI levels in patients with sepsis, sepsis-induced ARDS and septic shock in a relatively large prospective study." (PMID 26025445, 2015). "The objective of this study was to investigate whether single nucleotide polymorphisms (SNPs) in the TF and TFPI genes were associated with risk and outcome for patients with severe sepsis." (PMID 25407675, 2014). "Given the potential association of an activated coagulation system with sepsis pathophysiology, particularly the role of the TF pathway as an important initiator of the coagulation system, TF and TFPI were excellent candidate genes for severe sepsis susceptibility." (PMID 25407675, 2014). "Studies have detected high levels of TFPI in individuals with sepsis‐induced DIC, which coincide with high levels of TF, indicating an insufficiency of TFPI to counteract the TF‐triggered coagulation process." (PMID 39822757, 2025).
Sepsis (continued). "TFPI levels of sepsis patients were increased 2-fold at admission compared with baseline levels measured in samples from healthy volunteers." (PMID 39624584, 2024). "The active shedding of TFPI from EC surfaces by enzymes such as plasmin and neutrophil elastase has also been observed in human inflammatory conditions, including sepsis and acute lung injury." (PMID 39624584, 2024). "TFPI and antithrombin both poorly function in sepsis, largely due to the disturbed production of glycosaminoglycans on the endothelial surface to which TFPI is attached and which facilitates the function of antithrombin." (PMID 38950605, 2024). "Higher plasma concentrations of both tissue factor (TF) and tissue factor pathway inhibitor (TFPI) are associated with occurrence of disseminated intravascular coagulation (DIC), multi-organ dysfunction and increased mortality in patients with sepsis." (PMID 39478586, 2024). "The aim of this study was to test the discriminatory ability of E-selectin, EV, tissue factor (TF) and TF pathway inhibitor (TFPI) in sepsis-induced coagulopathy." (PMID 39624584, 2024). "The importance of E-selectin, EVs, TF, functional TF activity, and its counterpart TFPI was assessed in this prospective cohort study with sepsis patients, and TF-PCA and TFPI were identified as relevant factors." (PMID 39624584, 2024). "Especially TFPI levels were significantly elevated in sepsis patients who also scored for overt DIC at admission." (PMID 39624584, 2024). "As no reference ranges for the parameters EV concentration, TF procoagulant activity (TF-PCA), antigen levels, E-selectin, and TFPI concentrations were available, results were compared between sepsis patients and healthy volunteers." (PMID 39624584, 2024). "In the early stages of sepsis, three key anticoagulant pathways play a crucial role in regulating coagulation during sepsis: antithrombin, protein C, and tissue factor pathway inhibitor, yet these mechanisms are deranged as sepsis progresses." (PMID 38399545, 2024). "The anticoagulant pathways, represented by tissue factor pathway inhibitor (TFPI), anti-thrombin, and the protein C system, are compromised during sepsis and promote thrombus formation." (PMID 37569751, 2023). "Since coagulation activation in sepsis-associated DIC is primarily mediated through the TF/FVIIa pathway and the overexpression of TF compared with TFPI, the substitution of TFPI seems a rational treatment approach." (PMID 36673595, 2023). "The elevated levels of TFPI have been found in patients with sepsis-associated DIC in conjunction with elevated TF levels, suggesting a relative deficiency of TFPI to neutralize the TF pathway activation." (PMID 36673595, 2023). "The activation of the coagulation pathway during sepsis is accompanied by the inhibition of the three main anticoagulant systems: protein C (PC), AT, and TFPI." (PMID 37681852, 2023). "In sepsis, the levels and activity of AT, TFPI, and PC are significantly reduced in both animals and patients." (PMID 37681852, 2023). "The prothrombotic state in sepsis is intensified by impaired function of three main anticoagulant pathways, i.e., antithrombin, tissue factor pathway inhibitor (TFPI), and the protein C system." (PMID 36140361, 2022). "For example, results from clinical trials to evaluate the efficacy and safety of tifacogin (recombinant TFPI) to treat sepsis have so far been disappointing, emphasizing the complexity of the host response to systemic infection." (PMID 35913192, 2022). "Evidences also indicated that the lower levels of TFPI are strongly correlated with organ dysfunction as well as worse outcome of severe sepsis." (PMID 34804364, 2021). "During sepsis, the endothelium generates high levels of tissue factor pathway inhibitor (TFPI), together with NO and prostacyclin, in order to maintain an antithrombotic capacity." (PMID 35052592, 2021).
Sepsis (continued). "Several randomized controlled studies have been conducted using natural anticoagulants such as ATIII, recombinant human APC, recombinant human TFPI or recombinant human TM in patients with sepsis." (PMID 28288667, 2017). "This was taken to indicate that sepsis, in its own right, must be a strong trigger to the release of TFPI from the vascular endothelium." (PMID 26377606, 2016). "When the patients who had sepsis (n=38) were compared to patients with septic shock (n=13), we noted higher PT after 4 h and higher free TFPI after 4 and 12 h of enoxaparin administration." (PMID 26377606, 2016). "In the present study, we noted a trend towards higher TFPI levels and particularly free TFPI in patients with septic shock as compared to patients with sepsis." (PMID 26377606, 2016). "It has been reported that the imbalance between the levels of TF and TFPI seems to play a pivotal role in the pathogenesis of sepsis and ARDS." (PMID 26025445, 2015). "It has been reported that the lower levels of TFPI are strongly correlated with organ dysfunction as well as worse outcome of severe sepsis." (PMID 26025445, 2015). "Although some clinical studies found the plasma TF and TFPI levels are significantly changed in septic patients and correlated with the severity of sepsis, the results were controversial because of small sample size." (PMID 26025445, 2015). "Based on this model, ambitious clinical development programs of recombinant natural anticoagulants (antithrombin, TFPI, and rhaPC) in patients with sepsis were launched, going all the way to phase 3 trials and, in one case, market approval." (PMID 25943883, 2015). "Recent studies indicated that the dysfunction of TF and TFPI was closely related to the severity and outcome of sepsis." (PMID 25407675, 2014). "It has been reported that the lower TFPI levels were strongly correlated with organ dysfunction as well as worse outcome of severe sepsis." (PMID 25407675, 2014). "Seventeen SNPs in TF and TFPI were genotyped in samples of sepsis (n =577) and severe sepsis patients (n =476), and tested for association in this case–control collection." (PMID 25407675, 2014). "It should be noted that while rh-APC and rh-TFPI were infused in a continuous fashion in clinical trials of sepsis, in the reviewed preclinical studies these anticoagulants were nebulized intermittently." (PMID 22546487, 2012). "It should be mentioned that various infection models have shown a reduced sepsis-related mortality when animals were treated with tissue factor pathway inhibitor (TFPI)." (PMID 17660410, 2007). "In vivo experiments in baboon models of lethal DIC showed that TFPI is a potent inhibitor of sepsis-related mortality." (PMID 16504043, 2006). "Moreover, the propensity for thrombus formation during sepsis can be traced back to the simultaneous dysfunction of three significant anticoagulant pathways: antithrombin, TFPI, and the protein C system." (PMID 39445002, 2024). "EV-associated TF-PCA and TFPI levels were identified as significant discriminators of sepsis patients with overt DIC vs those without overt DIC." (PMID 39624584, 2024). "In addition to the role of TFPI in sepsis-induced ALI/ARDS, the activated protein C (APC) system is also significantly disrupted." (PMID 38664775, 2024). "Eighty-seven sepsis patients were recruited (35 with overt DIC) who presented with increased levels of EV, EV-associated TF procoagulant activity (TF-PCA), E-selectin, TF, and TFPI at admission compared with healthy subjects." (PMID 39624584, 2024). "Conversely, the anticoagulant pathways in sepsis, encompassing antithrombin, the protein C system, and tissue factor pathway inhibitor (TFPI), are severely compromised, leading to a reduction in antithrombin activity and an impairment of the functional capacity of activated protein C." (PMID 39445002, 2024).
Sepsis (continued). "So, one might speculate whether imbalances of TF/TFPI ratio contribute to microvascular alterations and subsequent organ dysfunctions, both of which are hallmarks of sepsis and septic shock." (PMID 38914630, 2024). "Thereby, the purpose was to examine if the ratio of TF/TFPI might function as a tool to identify those sepsis patients that are most likely to benefit from treatments that target the TF/TFPI pathway." (PMID 38914630, 2024). "The in vivo administration of recombinant TFPI (rTFPI) in experimental animal models prevented thrombosis and fibrin deposition on the subendothelial matrix, reduced mortality from Escherichia coli-induced sepsis, and protected against DIC development." (PMID 36673595, 2023). "There is evidence that the lower level of TFPI is closely related to sepsis." (PMID 37834169, 2023). "TF pathway inhibitor (TFPI) -predominantly expressed by endothelial cells- may be consumed and degraded in these conditions, as e.g. in patients with sepsis." (PMID 37638055, 2023). "In contrast, there was marked consumption of the natural coagulation inhibitors antithrombin, protein C, and protein S. These results go some way towards explaining why the therapeutic use of recombinant TFPI fails to correct sepsis-associated coagulopathy." (PMID 26377606, 2016). "Sepsis triggered marked release of TFPI from endothelial cells." (PMID 26377606, 2016). "Development of a procoagulant state in sepsis, due to aberrant expression of tissue factor (TF) and sharp decrease of its major inhibitor tissue factor pathway inhibitor (TFPI), could lead to microthrombotic organ failure." (PMID 27011792, 2016). "Earlier studies found deficiencies of the 3 main natural anticoagulants, antithrombin, protein C, and protein S. However, none of these inhibitors block tissue factor, the prime trigger of coagulation during sepsis that is controlled specifically by the tissue factor pathway inhibitor (TFPI)." (PMID 26377606, 2016). "Altered plasma levels of TF and TFPI have been related to worse outcome in sepsis." (PMID 25407675, 2014). "Moreover, deficiencies in natural anticoagulants (e.g., tissue factor pathway inhibitor (TFPI), antithrombin (AT III), and activated protein C (APC)) are often susceptible to sepsis, disseminated intravascular coagulation (DIC) consequences, and inflammation." (PMID 21941675, 2011). "Other studies have shown that active site-inhibited F VIIa (F VIIai) and TFPI reduce the expression of pro-inflammatory cytokines IL-6 and IL-8 in vivo, decrease coagulation and thereby prevent death in a lethal baboon model of Escherichia coli-induced sepsis." (PMID 17660410, 2007). "Recombinant TFPI was evaluated in a phase II randomized trial in patients with severe sepsis." (PMID 16504043, 2006). "Results of TFPI levels in sepsis patients are contradictory; while TF antigen levels were found to be an independent predictor of 30-day mortality in sepsis patients, this study did not detect significant differences in TFPI levels between healthy controls, patients with sepsis, and severe sepsis." (PMID 39624584, 2024). "However, the relationship between genetic polymorphisms of TF and TFPI and survival in patients with severe sepsis has not been examined." (PMID 25407675, 2014). "Release of cell surface HS anchored tissue factor pathway inhibitor (TFPI) may have benefit in early or pre-sepsis to reduce coagulation, although the potential benefit of heparin in the later stages of sepsis may be limited due to sepsis disruption of this pathway." (PMID 37259415, 2023). "Safety and efficacy of tifacogin, a recombinant form of human TFPI, were assessed in a phase III study (TFP007 OPTIMIST [Optimized Phase III Tifacogin in Multicenter International Sepsis Trial]) in patients with severe sepsis." (PMID 19284881, 2009).